SLC35F5 (solute carrier family 35 member F5)
Description:
Mediates choline transport, although the underlying transport mechanism remains to be elucidated.
Synonyms: FLJ22004
Tractability: Antibody: UniProt predicts a signal peptide or a membrane-spanning region. PROTAC: ubiquitination databases record sites on it.
Gene: Protein-coding gene on chromosome 2 (113,705,011 to 113,756,693, reverse strand). Ensembl gene ENSG00000115084.
Subcellular location: Membrane
Subcellular location (Human Protein Atlas): Plasma membrane
Gene Ontology:
Molecular function: choline transmembrane transporter activity
Biological process: choline transport
Cellular component: membrane
Genetic constraint (gnomAD): Loss-of-function variants: 31 observed, 36.1 expected, observed/expected ratio (o/e) 0.86, 90% interval 0.64 to 1.16. The upper end of that interval is the gene's LOEUF score, 1.16, which puts it in group 5 of 6, group 1 being the genes least tolerant of losing a copy. Missense variants: 385 observed, 418.81 expected, observed/expected ratio (o/e) 0.92, 90% interval 0.85 to 1. Synonymous variants: 151 observed, 139.72 expected, observed/expected ratio (o/e) 1.08, 90% interval 0.95 to 1.24.
Homologues: Orthologues: chimpanzee SLC35F5 (99% identical), pig SLC35F5 (96% identical), dog SLC35F5 (95% identical), mouse Slc35f5 (94% identical), rat Slc35f5 (93% identical), macaque SLC35F5 (93% identical), rabbit SLC35F5 (93% identical), guinea pig SLC35F5 (82% identical), tropical clawed frog SLC35F5 (64% identical), Drosophila melanogaster CG8195 (37% identical), Caenorhabditis elegans B0041.5 (24% identical).
Diseases named in the same sentence as SLC35F5 in open-access papers:
SLC35F5 is named in the same sentence as 1 disease in open-access papers, as found by Europe PMC text mining. Sharing a sentence is not in itself a finding about the gene and the disease. The quoted sentences say what the papers report.
non-small cell lung carcinoma (1 paper, 2019). A group of at least three distinct histological types of lung cancer, including non-small cell squamous cell carcinoma, adenocarcinoma, and large cell carcinoma. "The attenuation of deregulated miR-369-3p expression sensitizes non-small cell lung cancer cells to cisplatin via the modulation of the nucleotide sugar transporter SLC35F5." (PMID 31337985, 2019).